CLIP4 (CAP-Gly domain containing linker protein family member 4)
Synonyms: RSNL2; FLJ21069
Tractability: PROTAC: ubiquitination databases record sites on it; its protein half-life has been measured.
Gene: Protein-coding gene on chromosome 2 (29,095,545 to 29,199,777, forward strand). Ensembl gene ENSG00000115295.
Subcellular location (Human Protein Atlas): Vesicles
Gene Ontology:
Molecular function: protein binding; microtubule plus-end binding
Biological process: cytoplasmic microtubule organization
Cellular component: cell cortex; microtubule plus-end; nucleus
Genetic constraint (gnomAD): Loss-of-function variants: 30 observed, 56.53 expected, observed/expected ratio (o/e) 0.53, 90% interval 0.4 to 0.72. The upper end of that interval is the gene's LOEUF score, 0.72, which puts it in group 2 of 6, group 1 being the genes least tolerant of losing a copy. Missense variants: 721 observed, 746 expected, observed/expected ratio (o/e) 0.97, 90% interval 0.91 to 1.03. Synonymous variants: 245 observed, 261.92 expected, observed/expected ratio (o/e) 0.94, 90% interval 0.84 to 1.04.
Homologues: Orthologues: chimpanzee CLIP4 (99% identical), pig CLIP4 (92% identical), macaque CLIP4 (92% identical), dog CLIP4 (90% identical), guinea pig CLIP4 (90% identical), mouse Clip4 (88% identical), rabbit CLIP4 (82% identical), rat Clip4 (81% identical), tropical clawed frog clip4 (67% identical), zebrafish si:dkeyp-47f9.4 (34% identical). Paralogues in human: CLIP3 (43% identical), DCTN1 (20% identical), CLIP1 (19% identical), CLIP2 (18% identical).
Diseases named in the same sentence as CLIP4 in open-access papers:
CLIP4 is named in the same sentence as 22 diseases in open-access papers, as found by Europe PMC text mining. Sharing a sentence is not in itself a finding about the gene and the disease. The quoted sentences say what the papers report.
gastric cancer (4 papers, 2017 to 2021). A primary or metastatic malignant neoplasm involving the stomach. "The methylation of XKR6, CCDC57, MAML3, SDC2, and CLIP4 is associated with age and tumor location in gastric cancer." (PMID 33575272, 2020). "Third, bioinformatics and DNA methylomics showed that breast and gastric cancer tissues presented hyper-methylated CLIP4." (PMID 34965217, 2021). "The three genes used to assess GPSGC risk scores in our study (VCAN, CLIP4 and MATN3) have been previously reported to be associated with gastric cancer." (PMID 32754268, 2020). "We also observed a statistically significant association between gastric cancer diagnosis and promoter methylation of IRF4, ELMO1, CLIP4 and MSC, after adjusting for age and sex." (PMID 28418867, 2017). "Our findings suggest that IRF4, ELMO1, CLIP4 and MSC promoter methylation coupled with a GDMI>4 are useful molecular tools for gastric cancer risk stratification in endoscopic biopsies." (PMID 28418867, 2017). "Our findings suggest that promoter methylation of CLIP4, IRF4, ELMO1, and MSC, together with a GDMI > 4, is a useful molecular panel for gastric cancer risk stratification in endoscopic biopsies." (PMID 28418867, 2017). "Unlike previous reports, analyzing gastric cancer and ccRCC, this study showed that high CLIP4 expression was associated with a better prognosis, suggesting that CLIP4 had a suppressive function in breast cancer." (PMID 33575272, 2020). "Contrary to the results of this study, increased expression of four genes (CLIP4, NOX4, LAMP5, and MATN3) is related to poor prognosis, and the expression of these genes is higher in stromal components than in epithelial cancer cells in gastric cancer." (PMID 33575272, 2020). "Together these results suggest that promoter methylation of IRF4, ELMO1, CLIP4 and MSC may be part of a gastric cancer CpG island methylator phenotype (CIMP)." (PMID 28418867, 2017). "Promoter methylation of IRF4 (p < 0.0001), ELMO1 (p < 0.0001), CLIP4 (p < 0.0001), and MSC (p < 0.0001), is also associated with increasing severity from gastritis with no metaplasia to gastritis with metaplasia and gastric cancer." (PMID 28418867, 2017). "The promoter methylation of IRF4, ELMO1, CLIP4, and MSC is related with increasing seriousness from gastritis with no metaplasia to gastritis with metaplasia and gastric cancer." (PMID 33575272, 2020).
breast carcinoma (3 papers, 2016 to 2020). "To elucidate the molecular mechanism underlying the function of CLIP4 in breast cancer, we constructed a CLIP4-associated regulatory network." (PMID 33575272, 2020). "Analysis of epigenetic and genetic alterations of CLIP4 in breast cancer indicated that promoter methylation was the main mechanism underlying the regulation of CLIP4 gene expression." (PMID 33575272, 2020). "Close family members of CLIP4/UBASH3B were also found to be associated with metastasis in breast cancer, and the same study also suggested that CLIP4 expression could stimulate tumor metastasis in some tumor types." (PMID 27283491, 2016). "In the present study, the expression of CLIP4 was investigated in breast cancer by bioinformatics analysis." (PMID 33575272, 2020). "Oncomine and TCGA analysis revealed mRNA expression of CLIP4 to be significantly decreased in breast cancer, when compared to normal samples." (PMID 33575272, 2020). "Taken together, the combination of bioinformatic analyses demonstrated that CLIP4 was significantly downregulated in breast cancer." (PMID 33575272, 2020). "As a therapeutic target to overcome drug resistance in breast cancer, the JAK-STAT signaling pathway was associated with CLIP4 in this study." (PMID 33575272, 2020). "The present findings supported the important role of CLIP4 upregulation in tumor-associated signaling pathways such as Hh, JAK-STAT, Wnt, and ERBB, and suggested that it acted as a tumor suppressor in breast cancer." (PMID 33575272, 2020). "CLIP4 expression was dramatically lower in breast cancer than in normal tissues (p = 8.44E−53, <0.001)." (PMID 33575272, 2020). "Comparison of cancer and normal samples was performed to analyze the expression pattern of CLIP4 in breast cancer." (PMID 33575272, 2020). "In summary, the cytoplasmic linker protein CLIP4 may act as a novel prognostic and epigenetic biomarker for breast cancer patients." (PMID 33575272, 2020). "Finally, the regulation of the expression of CLIP4 in breast cancer was investigated by genetic and epigenetic analyses." (PMID 33575272, 2020). "Finally, there was a lack of in vivo and in vitro direct evidence to confirm the biological function and molecular mechanism of CLIP4 in breast cancer." (PMID 33575272, 2020). "MEXPRESS was used to confirm the promoter methylation status of CLIP4 in breast cancer." (PMID 33575272, 2020). "The prognostic role of CLIP4 in breast cancer was then investigated using the Kaplan-Meier Plotter, and the results demonstrated that higher expression of CLIP4 was associated with better RFS and OS, especially in Luminal B and HER2 positive breast cancers." (PMID 33575272, 2020). "The present findings on the association between CLIP4 and ERBB signaling in breast cancer may provide a novel research direction." (PMID 33575272, 2020). "Here, we first evaluated the expression profile of CLIP4 in breast cancer by data mining." (PMID 33575272, 2020). "In short, these results indicated that CLIP4 expression may play a favorable role in breast cancer patients." (PMID 33575272, 2020). "In summary, CLIP4 may be a novel prognostic indicator in breast cancer patients." (PMID 33575272, 2020). "However, the role of CLIP4 in breast cancer remains unknown." (PMID 33575272, 2020). "Furthermore, there have been no reports on the activity of CLIP4, CAPN2, CRLF1, CYBRD1, PHF10, and TRHDE in breast cancer or chemoresistance, thus making them new candidates for understanding breast cancer, the EMT, and chemoresistance." (PMID 27094684, 2016).
clear cell renal cell carcinomas (3 papers, 2016 to 2020). "In clear cell renal cell carcinoma (ccRCC), CLIP4 mutations are three-fold higher in patients with aggressive tumors than in those without aggressive ccRCC, and high expression levels of MOCOS, BAIAP2L1, DDX11, and CLIP4 are markedly associated with poor OS." (PMID 33575272, 2020).
adenoma (2 papers, 2019 to 2021). A neoplasm arising from the epithelium. "They target CpG sites located in the 5′-regions of the genes C9orf50, KCNQ5, and CLIP4 that were found to be concurrently hypermethylated in CRC and adenoma tissues, but unmethylated in blood cells and in most other cancer types." (PMID 31727158, 2019).
colorectal cancer (2 papers, 2019 to 2020). A primary or metastatic malignant neoplasm that affects the colon or rectum. "Three DNA methylation markers, C9orf50, KCNQ5, and CLIP4, can discriminate between the plasma from colorectal cancer patients and that of healthy individuals." (PMID 33575272, 2020). "Three DNA methylation markers, C9orf50, KCNQ5, and CLIP4, were identified, each capable of discriminating plasma from colorectal cancer patients and healthy individuals (areas under the curve 0.86, 0.91, and 0.88)." (PMID 31727158, 2019).
gastritis (2 papers, 2017 to 2020). Inflammation of the stomach. "Promoter methylation of IRF4 (p < 0.001), ELMO1 (p < 0.001), CLIP4 (p < 0.001), and MSC (p < 0.001), is strongly associated with increasing severity of disease in the histological progression from gastritis with no metaplasia, to gastritis with metaplasia, to gastric adenocarcinoma." (PMID 28418867, 2017).
kidney cancer (2 papers, 2016 to 2020). Primary or metastatic malignant neoplasm involving the kidney. "CLIP4 shows high expression levels in kidney cancer cell lines compared with normal cell lines, and CLIP4 significantly increases cell migration and viability." (PMID 33575272, 2020). "CLIP4 exhibited high fold-changes in expression levels in all kidney cancer cell lines compared to normal kidney cell lines." (PMID 27283491, 2016). "qRT-PCR was performed on all six cell lines for the three candidate genes (RELN, FOXC2, and CLIP4) to identify those with significant fold-changes in gene expression in the kidney cancer cell lines compared to the normal kidney cell line." (PMID 27283491, 2016). "CLIP4 demonstrated high fold-changes in all kidney cancer cell lines compared to the normal kidney cell line." (PMID 27283491, 2016).
nephritis (2 papers, 2014 to 2016). Inflammation of renal tissue. "Autoreactive IgE’s to APEX, MPG, and CLIP4 also showed a highly significant association with hypocomplementemia and with active nephritis." (PMID 24587356, 2014). "We also reported novel autoantigens by protein array screening as being associated with active nephritis and hypocomplementemia: APEX nuclease 1 (APEX), N-methylpurine-DNA glycosylase (MPG), and CAP-GLY domain containing linker protein family member 4 (CLIP4)." (PMID 31557984, 2016).
ductal breast carcinoma (1 paper, 2020). "The CLIP4 expression was significantly decreased in invasive breast carcinoma, invasive lobular breast carcinoma, invasive ductal breast carcinoma, tubular breast carcinoma, mucinous breast carcinoma, ductal breast carcinoma in situ, and mixed lobular and ductal breast carcinoma." (PMID 33575272, 2020).
invasive breast carcinoma (1 paper, 2020). A carcinoma that infiltrates the breast parenchyma. "Genetic alterations of CLIP4 were mutually exclusive and only found in 11 (1.1%) of 963 invasive breast carcinoma patients, of which six samples had DNA amplification, two had deep deletion, two had a truncating mutation, and one had a missense mutations." (PMID 33575272, 2020).
lung adenocarcinoma (1 paper, 2020). A carcinoma that arises from the lung and is characterized by the presence of malignant glandular epithelial cells. "Interestingly, potentially pathogenic mutations of CLIP4 and other genes may state a subset of lung adenocarcinoma among never-smoking women." (PMID 33575272, 2020).
renal cell carcinoma (1 paper, 2023). "As a promising molecule for predicting metastasis, increased expression of CLIP4 in renal cell carcinoma may dramatically increase cell viability and migration." (PMID 38074856, 2023).
triple-negative breast carcinoma (1 paper, 2020). An invasive breast carcinoma which is negative for expression of estrogen receptor (ER), progesterone receptor (PR), and human epidermal growth factor receptor 2 (HER2). "However, the expression of CLIP4 was markedly upregulated in basal-like and triple-negative breast cancer (TNBC) (basal-like status: p < 0.0001; triple-negative status: p < 0.0001)." (PMID 33575272, 2020).
tumor (14 papers, 2016 to 2025). "For instance, CLIP4 is involved in regulating the expression of several tumor-associated genes, and its expression is considered to stimulate tumor metastasis; for KIRC, gene CLIP4 was identified as an O-LNE biomarker." (PMID 35668489, 2022). "Some studies have shown that CLIP4 expression stimulates tumor metastasis and recurrence in certain tumor types, and its promoter methylation is associated with an increase in GC severity 36-38." (PMID 32754268, 2020). "CLIP4 was reported to regulate the expression of several genes associated with tumor invasiveness and metastasis, and the promoter methylation of CLIP4 might be involved in the pathogenesis of GC." (PMID 33330065, 2020). "Although a CLIP4 signal in plasma suggests the presence of tumor DNA when corroborated by KCNQ5 or C9orf50, the suboptimal performance of CLIP4 in gastric and GEJ cancers should be noted." (PMID 39369091, 2025). "In KIRC, CLIP4 was identified as an O-LNE biomarker; CLIP4 is involved in regulating the expression of several tumor-associated genes, and its expression is considered to stimulate tumor metastasis." (PMID 35668489, 2022). "Similarly, the upregulation of miR-135b-5p in gastric cancer promotes tumor invasiveness by targeting CLIP4, thereby impairing the tumor-suppressive JAK2/STAT3 signaling pathway." (PMID 41229433, 2025). "Furthermore, representative cases consisting of 20 CRC patients, 10 CA patients and 10 healthy controls were chosen to detect the CLIP4 methylation status in serum and colorectal normal or tumor tissue from the same patient." (PMID 34965217, 2021). "Despite many studies providing important data and tumor-specific roles for CLIP4 in human cancer, its biological function and molecular mechanism remain unclear." (PMID 33575272, 2020). "A prospective study examining frozen tissue qRT-PCR of AQP1, DDX11, BAIAP2L1, and six previously identified genes (PBRM1, BAP1, SETD2, KDM5C, FOXC2, and CLIP4) showed that expression of DDX11 was a significant factor for predicting tumor aggressiveness based on Fuhrman grade." (PMID 31963294, 2020). "However, considering that the details of how CLIP4 influences tumor progression are still unclear, further research on the functional role and mechanism(s) of CLIP4 is needed." (PMID 27283491, 2016). "Furthermore, CLIP4 has been considered a promising epigenetic biomarker by analysis of differentially methylated genes and differentially expressed genes between matched tumor and non-tumor tissues of the colon." (PMID 33575272, 2020). "Moreover, regulation of FOXC2 and CLIP4 expression, which could suppress cell migration and inhibit tumor metastasis, would provide future helpful anti-cancer strategies to improve the survival of patients with metastatic ccRCCs." (PMID 27283491, 2016). "In our previous studies, we have demonstrated a high sensitivity of ctDNA detection using the TriMeth test, a tumor-agnostic multiplex droplet digital PCR assay targeting the gastrointestinal cancer-specific DNA methylation markers, C9orf50, KCNQ5, and CLIP4." (PMID 39369091, 2025). "Conversely, a set of genes, namely CLIP4, HAS2, and KCTD12 (p < 0.01), were found to be notably downregulated in tumor cells." (PMID 38549669, 2024). "The tissue distribution and cell location of VCAN, CLIP4 and MATN3 proteins suggest their relevance to the tumor microenvironment (TME) 27-29." (PMID 32754268, 2020). "The tissue distribution and cell localization of the VCAN, CLIP4 and MATN3 proteins suggest their relevance to the tumor microenvironment (TME)." (PMID 32754268, 2020). "Frozen tumor tissues and plasma were used to measure PBRM1, BAP1, SET domain-containing 2 (SETD2), KDM5C, FOXC2, CLIP4, AQP1, DDX11, BAIAP2L1, and TMEM38B mRNA levels, and correlation with the Fuhrman grade was investigated." (PMID 32392781, 2020). "CLIP4 expression was negatively correlated with HER2 status, NPI, SBR grade, nodal status, and tumor stage." (PMID 33575272, 2020).
tumor (continued). "Therefore, we infer that the effect of VCAN, CLIP4 and MATN3 expression on the poor survival of GC patients is probably related to the remodeling of stromal components in the tumor microenvironment." (PMID 32754268, 2020). "Secondly, because tumor size is an important determinant of the likelihood of synchronous metastasis also in patients with ≤7-cm ccRCCs, the relationship between the tumor size and the expression of FOXC2 and CLIP4 should be clarified." (PMID 27283491, 2016). "Prior to this study, link between CLIP4 and tumor metastasis had not yet been clearly identified." (PMID 27283491, 2016). "The methylation of other genes, CLIP4, XKR6, CCDC57, MAML3 and SDC2, was related with one or more of the following variables: age, tumor location, and Helicobacter pylori infection, rather than with the histologic subtype." (PMID 28418867, 2017).
cancer (6 papers, 2016 to 2025). A tumor composed of atypical neoplastic, often pleomorphic cells that invade other tissues. "Previous studies have linked CYB5R3 and CLIP4 to cancer diagnosis and prognosis." (PMID 38074856, 2023). "To identify the roles of CLIP4 in cancers, we searched the Oncomine dataset for CLIP4 mRNA expression in common cancer types." (PMID 33575272, 2020). "Hh signaling pathway, JAK-STAT signaling pathway, cell adhesion molecules, ERBB signaling pathway, Wnt signaling pathway, and pathways in cancer were differentially enriched in the CLIP4-high expression phenotype." (PMID 33575272, 2020). "The level of CLIP4 methylation in cancer tissues was much higher than in adjacent tissues [51." (PMID 38074856, 2023). "Recent research on CLIP4 uncovered its potential functions in cancers." (PMID 33575272, 2020). "CLIP4, as a member of the CAP-Gly domain containing linker protein (CLIP) family, which is involved in plus-end binding of microtubules, has been implicated in immune response-related biological processes, cell migration and viability in certain cancer metastases." (PMID 34965217, 2021). "However, the association of CLIP4 with Wnt signaling and cytoskeletal proteins in human cancers has not been reported to date." (PMID 33575272, 2020). "However, the role of the cytoskeleton and microtubule-associated protein CLIP4 in human cancer has not been studied extensively." (PMID 33575272, 2020). "In line with this study, 43 genes (including CLIP4) were downregulated in ovarian cancer tumor samples and reactivated after treatment with 5-Aza-2'-deoxycytidine (5-aza-dC); CLIP4, GULP1, BAMBI, NT5E, and TGFB2 showed a pattern of cancer-specific methylation." (PMID 33575272, 2020). "In the analysis of genes co-expressed with CLIP4, GSEA showed that the Hedgehog (Hh), JAK-STAT, ERBB, Wnt signaling pathway, cell adhesion molecules, and pathways in cancer were dissimilarly enriched in the CLIP4 expression high phenotype." (PMID 33575272, 2020). "Thus, a study involving several cancer types should be conducted to verify the specificity of hyper-methylated CLIP4 and CK20/hyper-methylated CLIP4 for CRC diagnosis." (PMID 34965217, 2021). "Collectively, these data suggest that overexpression of FOXC2 and CLIP4 likely increases cell migration, which correlates to the synchronous metastasis of early-stage RCCs, whereas RELN may aid cancer cell survival." (PMID 27283491, 2016).
CLIP4 also shares sentences with these, for which no sentence is quoted: ductal breast carcinoma in situ (1 paper); gastric adenocarcinoma (1); infection (1); invasive ductal breast carcinoma (1); invasive lobular breast carcinoma (1); systemic lupus erythematosus (1); tubular breast carcinoma (1).